IL4 (interleukin 4)
Diseases named in the same sentence as IL4 in open-access papers (continued):
Sharing a sentence is not in itself a finding about the gene and the disease.
pancreatic cancer (continued). "Even more, suppression of IL-4 mRNA in the liver of cachexia patients with pancreatic cancer and improved performance of carcinoma-bearing mice treated by IL-4 may provide beneficial approaches for pancreatic cancer patients suffering from tumor-induced cachexia in the future." (PMID 33804263, 2021). "The mechanisms of how the IL-4/IL-13 cytokine-receptor system can influence the pathogenesis of other cancers may also provide new insights for further investigating their roles in pancreatic cancer." (PMID 33804263, 2021). "First, IL-4 may act as an autocrine growth factor in pancreatic cancer cells." (PMID 15714203, 2005). "It is also possible that the expression of the IL-13Rα1 chain, which associates with the IL-4Rα chain to form a functional receptor, may influence the effects of exogenous IL-4 although MIA PaCa-2 cells as well as the other pancreatic cancer cells lines express IL-13Rα1." (PMID 15714203, 2005). "Previous mouse models have shown that, by targeting Interleukin-4, an inhibitory cytokine expressed by the TME in pancreatic cancer, next generation anti-PSCA CAR T-cells were able to eliminate tumor cells." (PMID 36428811, 2022). "In this study, we show that FAK expressed in kras mutant murine pancreatic cancer cells regulates the expression of IL6, which acts to amplify IL4-dependent expression of the immune checkpoint ligand PD-L2 within the PDAC TME." (PMID 36138073, 2022). "Furthermore, the combination of inhibiting the IL-4/IL-13-receptor axis with chemotherapeutics, radiotherapy, and/or other small inhibiting molecules may provide attractive possibilities with high efficiency and specificity for pancreatic cancer treatment." (PMID 33804263, 2021). "The IL-4/IL13-receptor axis is believed to be overexpressed and play an important role in pancreatic cancer." (PMID 33804263, 2021). "In vivo, SmarT cells expanded, persisted, and eliminated pancreatic tumors expressing PSCA, TGFβ, and IL-4, with minimal expansion/persistence at tumor sites expressing PSCA only." (PMID 30828333, 2019). "SmarT cells demonstrated the ability to recognize PSCA antigen on pancreatic cancer cells through the CAR, induce costimulation via TGFβ induced activation of 41BB, and initiate cytokine signaling through 4/7-ICR in the presence of IL-4." (PMID 30828333, 2019). "Our results confirmed that the expression level of CCL18 in pancreatic cancer was significantly higher than that in corresponding normal pancreatic tissues and that CCL18 is the most abundantly expressed cytokine in IL-4-activated M2 macrophages." (PMID 29670110, 2018). "First, the IL-4-dependent tyrosine phosphorylation of IRS-1 and -2, overexpressed in human pancreatic cancer, was analysed." (PMID 15714203, 2005). "In the present study, we demonstrated for the first time that IL-4 activates MAPK and Akt in IL-4-responsive pancreatic cancer cells." (PMID 15714203, 2005). "Moreover, clinical studies showed the safety and efficacy of several reagents targeting IL4 and IL13 receptors in pancreatic cancer." (PMID 35207737, 2022). "As cytokines such as IL-4 and IL-13 play a vital role in the interaction of tumour cells and components of the TME, their understanding is crucial in order to design better therapies for pancreatic cancer." (PMID 35409019, 2022). "This way, we were able to examine the oncogenic effects of the IL-4-signaling-axis without exogenous influence and thus as close as possible to its in vivo influence in growth and spread of pancreatic cancer." (PMID 28350325, 2017). "We found that both IFN-γ and IL-4 treatment resulted in a marked increase of B7-H3 on SU86.86 but not on Panc-1 pancreatic cancer cells." (PMID 20035626, 2009). "Moreover, IL4, IL6, IL8, and IL21 receptors are overexpressed on the surface of various cancer cells, including bladder, ovarian, breast, colon, head and neck, lung, and pancreatic cancer." (PMID 40886193, 2025).
pancreatic cancer (continued). "Finally, using multiplex analysis, we find that IL-5, but not IL-4 or IL-13 is hypersecreted from colon and pancreas tumors obtained from mice treated with Th2 cells." (PMID 36376448, 2023). "In pancreatic cancer, IL-13 or IL-4 is not studied in clinical trials currently." (PMID 35409019, 2022). "Pancreatic cancer cells were determined to express the transcription factors STAT1, STAT3, and STAT6 at various levels, while Stat3 phosphorylation was enhanced in response to IL-4 stimulation, and STAT6 nuclear translocation was increased after exposure to IL4." (PMID 33804263, 2021). "In IL-4-nonresponsive MIA PaCa-2 cells, IGF-I but not IL-4 enhanced MAPK and Akt activity, suggesting that MAPK and Akt activation are essential for IL-4-induced cell proliferation in pancreatic cancer cells." (PMID 15714203, 2005).
schizophrenia (42 papers, 2010 to 2025). A major psychotic disorder characterized by abnormalities in the perception or expression of reality. "Network analyses indicate tumor necrosis factor (TNF), interleukin-4 (IL-4), and interferon-γ (IFNγ) as predominant functional nodes in the relationship between lithium response and schizophrenia genetic predisposition." (PMID 33804842, 2021). "Alteration in IL-4 levels in schizophrenia patients is reportedly linked to neurodevelopmental outcomes with immune dysregulation." (PMID 32038109, 2020). "Further studies of the molecular mechanisms underlying the IL4 X SOB interaction might suggest novel immunomodulatory strategies for prevention of schizophrenia." (PMID 29464121, 2017). "For example, several interleukin genes (IL2, IL3, IL4) have been implicated for schizophrenia." (PMID 20613869, 2010). "In this study, IL-4 levels in schizophrenia patients were too low for detection at baseline and remained unchanged after six months of antipsychotic treatment." (PMID 39796241, 2025). "Compared with healthy people, IL-6 and TNF-α levels were significantly increased in schizophrenia patients, while IL-2, IL-4 and IFN-γ levels were significantly decreased." (PMID 37582716, 2023). "The involvement of IL-4 in the pathogenesis of schizophrenia has been widely investigated, yet published data remain highly heterogeneous." (PMID 36139363, 2022). "The cytokines produced by Th2 (IL-4, IL-5, and IL-13) were also increased in patients with schizophrenia (P < 0.001; P < 0.001; P = 0.012, respectively)." (PMID 35223927, 2022). "Nevertheless, the role of IL-4 in schizophrenia-related disturbances remains ambiguous and undoubtedly requires further investigation." (PMID 36139363, 2022). "In contrast, the ET, IL-4, and LPS acute signatures were all enriched amongst the genes increased in the medium illness duration group of participants with schizophrenia compared to controls." (PMID 34054608, 2021). "In regard to studies with only serum samples, correlations between [IFN-γ]/[IL-4] and [kynurenine]/[tryptophan] were found in schizophrenia." (PMID 32061259, 2020). "The results of the present systematic review highlight that patients with schizophrenia seem to show lower plasma concentration of IL-4." (PMID 32061259, 2020). "The classification accuracy of combined cytokines, IL-4, IL-6 and IL-12, was 79% and cross-validation accuracy was 79% for schizophrenia patients with NSS compared with healthy controls." (PMID 32038109, 2020). "The AUCs for the combined cytokines (IL-4, IL-6 and IL-12) was 0.75 (95% CI = 0.69 - 0.80) between schizophrenia patients and healthy controls." (PMID 32038109, 2020). "The effective classification accuracy of the combination (IL-4, IL-6 and IL-12) was 77% and the cross-validation accuracy was 76% in schizophrenia patients." (PMID 32038109, 2020). "The plasma levels of IL-4 indicated a good ability to classify schizophrenia patients with NSS versus healthy controls (AUC = 0.86)." (PMID 32038109, 2020). "Previous studies have also reported that plasma IL-4 concentration is lower in unmedicated schizophrenia patients." (PMID 32038109, 2020). "Only one cytokine from the γ-chain-cytokine family, namely IL-4, was related to the kynurenine pathway in schizophrenia." (PMID 32061259, 2020). "On the one hand, one included study evidenced significant correlations between IFN-γ/IL-4 in plasma and tryptophan breakdown ratio ([kynurenine]/[tryptophan]) in schizophrenia." (PMID 32061259, 2020). "We focused on two factors: the pro-inflammatory IL-6, which has a potential role in the induction of schizophrenia-like behavioural disturbances, and the anti-inflammatory IL-4, which is the main cytokine regulating the CD200–CD200R axis." (PMID 32664639, 2020). "Patients with schizophrenia had elevated levels of IL-4 and increased production of TGF-β, which suggested the link between this psychiatric condition and chronic inflammatory processes." (PMID 30374300, 2018).
schizophrenia (continued). "Using five of these biomarkers (sTNF-R1 and sTNF-R2, CCL11, CXCL10, IL-4), the authors found a sensitivity of 70% and specificity of 89.4% for the diagnosis of schizophrenia." (PMID 28870209, 2017). "Genetic variants in the 5q region have previously been found to be associated with schizophrenia (e.g., IL3, IL4, IL9, NEUROG1)." (PMID 22723893, 2012). "In schizophrenia, neuroinflammation denotes the initiation of the brain’s immune response, which is principally driven by microglial cells and the discharge of inflammatory cytokines like IL-2, IL-4, IL-13 IFN-γ, and TNF-α." (PMID 38256307, 2023). "However, in line with the inconsistency related to basal IL-4 levels in schizophrenia, there is also contradictory evidence concerning the effects of pharmaceuticals on this cytokine." (PMID 36139363, 2022). "Notably, IL-4 and IL-10 elevations were highly significant in this meta-analysis, but are less frequently identified in patients with schizophrenia." (PMID 29803226, 2018). "In fact, according to the literature, increased TNF-α/IL-4 and IFN-γ/IL-4 ratios were verified in BP patients during manic episodes as compared with normal controls, and a relative predominance of the Th2 immune profile was evidenced in patients with acute exacerbation of schizophrenia." (PMID 38644495, 2024). "There are no data on the impact of combinations of antipsychotics in TRS patients on other cytokines, e.g., IL-2, IL-4, IL-5, IL-10, IL-12, IL-17, IL-23 and TGF-β1, although their involvement in schizophrenia pathophysiology has been demonstrated." (PMID 39595201, 2024). "IL-1β, IL-2, IL-4, IL-6, BAFF, IFN-α, GM-CSF, NRG1-β1, and GDNF increased but TNF-α and NGF-β decreased in schizophrenia compared to healthy individuals." (PMID 37239308, 2023). "Cytokine levels including IL-2, IL-4, IL-6, IL-10, TNF-α, and IFN-γ were tested, and we found significantly higher levels of IL-6 in patients with schizophrenia (P < 0.01)." (PMID 38066312, 2023). "Moreover, the compensatory immune regulatory system (CIRS), which may attenuate an overzealous inflammatory response, is activated in affective disorders and schizophrenia and these include T regulatory (Treg) (e.g., IL-10) and Th2 (e.g., IL-4, IL-9, and IL-13) profiles." (PMID 35641947, 2022). "Data from 62 studies, analyzed IFN-γ, IL-4, IL-2, soluble IL-2 receptor (sIL-2R), IL-1β, IL-1 receptor antagonist (IL-1RA), TNF-α, IL-6, soluble IL-6 receptor (sIL-6R), and IL-10 in schizophrenia." (PMID 33746786, 2021). "The results of the present systematic review revealed the following cytokines as possible candidates for deregulatory mechanisms on the kynurenine pathway in schizophrenia: TNF-α, IFN-γ, IL-6, IL-4, IL-8, and IFN-α." (PMID 32061259, 2020). "Among the cytokines analyses in the peripheral blood, we found that IL-4 levels were more discriminatory than others, though comparison of EOS patients and healthy controls had a higher AUC than for schizophrenia patients and AOS patients." (PMID 32038109, 2020). "We determined the plasma levels of six cytokines (IL-1β, IL-4, IL-6, IL-10, IL-12 and TNF-α) in schizophrenia patients and healthy controls." (PMID 32038109, 2020). "Clozapine has previously been shown to decrease production of IFN-γ and enhance IL-4 and IL-10 in poly (I:C)-stimulated PBMC cultures from schizophrenia patients, which suggests an effect on CD4+ T cell differentiation." (PMID 28356108, 2017). "Thus, the revealed complex of immunological indicators (IL-8, CIC, IL-4, IFN-γ, TNF-α, cortisol) is significant for diagnosing schizophrenia." (PMID 39944368, 2023). "The signs of activation of Th2 immune response in schizophrenia include the increase of the IL-4 and IL-10 levels in blood serum, decrease of Th1/Th2 cytokine level ratio (IFN-γ/IL-4, IFN-γ/IL-10, IL-2/IL-4, TNF-α/IL-4)." (PMID 39944368, 2023).
schizophrenia (continued). "IL-4 decreased non-significantly following treatment in schizophrenia (g: −0.84; CI −1.86 to 0.18; p = 0.11; I2 = 97%) whereas in MDD IL-4 increased non-significantly (g: 1.47; CI −0.83 to 3.78; p = 0.210; I2 = 96%)." (PMID 33653423, 2021). "Finally, in patients with schizophrenia, the Th1/Th2 ratio (defined as [IFN-γ]/[IL-4]) showed a significant positive correlation with admission levels of plasma IL-6 and plasma TNF-α." (PMID 32061259, 2020). "Likewise, adolescents experiencing their initial episode of schizophrenia exhibited a strong correlation between negative symptoms and the elevated levels of IL-4." (PMID 38807424, 2024). "Here, we analyzed changes in serum concentrations of cytokines (IL-1β, IL-2, IL-4, IL-6, IL-10, IL-21, APRIL, BAFF, PBEF/Visfatin, IFN-α, and TNF-α) and growth/neurotrophic factors (GM-CSF, NRG1-β1, NGF-β, and GDNF) in patients with schizophrenia in an exacerbation phase." (PMID 37239308, 2023). "Elevated IL-6 levels in childhood might lead to the development of schizophrenia in young adulthood 30, and significant correlations have been found between anti-inflammatory IL-4 and IL-10 with negative symptoms in EOS patients." (PMID 32038109, 2020). "Our study is the first to raise the intriguing possibility that the MIA-induced disturbances in the CD200–CD200R system, as well as its negative (IL-6) and positive (IL-4) immune regulators, determine the manifestation of the schizophrenia-like behavioural disturbances." (PMID 32664639, 2020). "In a study, the diagnosis of schizophrenia was accompanied by a specific cytokine-chemokine profile, i.e., increased levels of CCL11, CCL3, soluble TNF receptors 1 and 2 (sTNF-R1 and sTNF-R2), and decreased levels CXCL10 (also known as IFN-Υ-inducible protein 10 or IP-10), TNF-α, IL-2, and IL-4." (PMID 28870209, 2017). "Elevations of IL-1β, IL-6, IL-8, IL-4, and TNF-α may also exacerbate negative symptoms of schizophrenia, whereas IL-6, together with IL-13 and IL-17, may intensify general symptoms in chronic schizophrenia." (PMID 40364201, 2025).
lymphoma (41 papers, 2004 to 2025). A malignant (clonal) proliferation of B- lymphocytes or T- lymphocytes which involves the lymph nodes, bone marrow and/or extranodal sites. "As a signature type 2 cytokine, IL-4 has been implicated in SS pathogenesis, particularly in cases with evident ectopic germinal centers or those complicated by lymphoma, a known late-stage complication of SS35." (PMID 39820778, 2025). "Increased expression of lymphoma-infiltrating Tfh cells was associated with high levels of IL-6, IL-21, IL-4, and CXCL13." (PMID 36578079, 2022). "This highlights the oncogenic importance of IL-4/STAT6 pathway dysregulation across multiple lymphoma subtypes, not only MF." (PMID 40864740, 2025). "Further study is needed to clarify IL-4’s net influence on the BV response in CD30+ lymphomas, including MF." (PMID 40864740, 2025). "First, the systemic inflammatory cytokines produced by lymphoma cells, such as IL-4, IL-5, and TNF-α, can increase pruritus and facilitate the development of pruritic nodules." (PMID 39911286, 2025). "In NHL, STAT6 is essential for IL-4 and IL-13 signaling, which supports Th2-mediated immune responses and aids in the survival and growth of lymphoma cells." (PMID 40321894, 2025). "We show that IL4 treatment induced RRAGD expression, that RRAGD is required for mTOR activation in lymphoma cells and that IL4-enhanced BCR signaling induced mTOR activation." (PMID 39910284, 2025). "In conclusion, our study provides valuable insights into the potential association between IL-4, BDNF, neopterin, and depressive symptoms in lymphoma patients undergoing R-CHOP chemotherapy." (PMID 39355088, 2024). "The purpose of the study was to investigate the association between levels of IL-4, BDNF, neopterin, and depressive symptoms in lymphoma patients receiving consecutive cycles of chemotherapy." (PMID 39355088, 2024). "This study aims to address this gap by investigating the association between IL-4, BDNF, neopterin and depressive symptoms in lymphoma patients." (PMID 39355088, 2024). "The expression levels of IL-4 and IL-6 were low in WT group and KO group, but they significantly increased in WT + lymphoma cell group, suggesting that lymphoma cells can activate IL-4 and IL-6 in bone marrow-derived macrophages." (PMID 38261741, 2024). "The expressions of IL-4 and IL-6 in KO + lymphoma cell group were significantly inhibited compared with WT + lymphoma cell group, demonstrating that Notch-1 is a key upstream molecule regulating the expressions of IL-4 and IL-6." (PMID 38261741, 2024). "Binding of IL-4 to its receptor (IL-4R) on lymphoma cells recruits JAK1/3 and activates STAT6 by phosphorylation of Y641." (PMID 35851155, 2022). "RNA sequencing identified PARP14 -a transcriptional switch and co-activator of STAT6- among the top differentially upregulated genes in IL-4 stimulated STAT6MUT lymphoma cells and in STAT6MUT primary FL cells." (PMID 35851155, 2022). "Our data support a model in which increased PARP14 levels drive a self-reinforcing microcircuit that promotes the assembly of the STAT6 enhanceosome complex in IL-4 stimulated STAT6MUT lymphoma cells, thereby further amplifying STAT6-dependent gene activation." (PMID 35851155, 2022). "The tumor-promoting M2 LAMs can be induced under the influence of the cytokines (IL-4, IL-13, IL-10 and M-CSF) produced by the lymphoma cells and the microenvironment." (PMID 34527580, 2021). "One of them has an increased expression of IL-4 relative to CD3 expression levels, which are significantly associated with lymphoma progression." (PMID 34948183, 2021). "Interleukin (IL)-4 has been confirmed to be elevated in HL and follicular lymphoma; moreover, IL-4 not only contributes to the abnormal proliferation of lymphoma cells but also prevents malignant lymphocytes from apoptosis." (PMID 34079795, 2021). "The cytokines IL-4, IL-6, IL-10 and TNFα are produced by T cells, but often also by activated lymphoma cells or macrophages." (PMID 32899476, 2020).